HJV (hemojuvelin BMP co-receptor)
Diseases named in the same sentence as HJV in open-access papers (continued):
Sharing a sentence is not in itself a finding about the gene and the disease.
coronary artery disease (1 paper, 2015). "Notably, two previous studies reported the SNPs rs12091564 and rs10218795 in the hemochromatosis type 2 gene (HFE2; also known as hemojuvelin [HJV]) to be associated with coronary artery disease (CAD) based on a two-marker association test and haplotype analysis." (PMID 26159428, 2015).
liver cancer (1 paper, 2019). An epithelial or non-epithelial malignant neoplasm that arises from the liver. "A few studies suggest that BMP6 and HJV, which are inhibited in liver cancer, are the main regulator of hepcidin expression, while studies have also shown that the low expression of hepcidin predicts poor prognosis in liver cancer patients." (PMID 31052210, 2019).
muscle atrophy (1 paper, 2025). The loss of muscle tissue due to inactivity or disease. "In this study, we explored the involvement of HJV in disuse-induced muscle atrophy and uncovered the potential mechanisms." (PMID 40076640, 2025). "In this study, we also found that HJV expression was reduced in atrophied muscles due to disuse, and muscle-specific Hjv knockout aggravated disuse-induced muscle atrophy by promoting the expression of Atrogin-1 and MuRF1." (PMID 40076640, 2025).
Obesity (1 paper, 2022). Accumulation of substantial excess body fat. "Meanwhile, blood concentration of soluble HJV was significantly increased in obese patients compared to controls, suggesting that the adipose tissue may have a role in iron homeostasis in obesity and in erythropoiesis through the action of HJV." (PMID 36335331, 2022).
cancer (4 papers, 2013 to 2025). A tumor composed of atypical neoplastic, often pleomorphic cells that invade other tissues. "Moreover, association between both hepcidin regulatory genes (HFE and HJV) was found in all grades and stages of this disease, except stages IIIB and IV of cancer." (PMID 24078156, 2013).
genetic diseases (3 papers, 2020 to 2025). "Juvenile haemochromatosis type 2A (JH 2A) is an autosomal recessive genetic disorder characterized by disrupted iron metabolism regulation and progressive iron overload due to HJV gene variation." (PMID 40587672, 2025).
tumor (2 papers, 2013 to 2022). "According to QPCR data, the expression profiles of HJV, IRP2, TfR2 and miR-149 genes were dependent on depth of tumor invasion." (PMID 24078156, 2013).
endocrinopathies (1 paper, 2020). "Mutations in the genes of hepcidin or HJV can be the cause for the development of juvenile form of this disease which develops fast, and it is accompanied by severe damages including cardyomyopathy and endocrinopathies." (PMID 31659405, 2020).
HJV also shares sentences with these, for which no sentence is quoted: infection (4 papers); liver fibrosis (4); type 2A hemochromatosis (3); cardiomyopathy (2); colitis (2); E. coli infection (2); iron overload disease (2); acute leukemia (1); anaemia (1); astrocytoma (1); bacterial infection (1); brain tumors (1); diabetes (1); heart failure (1); Hydrocephalus (1); hyperferritinemia (1); ischemic stroke (1); leishmaniasis (1); liver cirrhosis (1); liver disease (1); lung carcinoma (1); myeloma (1); neurodegenerative disease (1); ovarian carcinoma (1); Parkinson disease (1); prostate carcinoma (1); steatosis (1); Stroke (1); viral infection (1); vitamin A deficiency (1).